FABP5 (fatty acid binding protein 5)
Diseases named in the same sentence as FABP5 in open-access papers (continued):
Sharing a sentence is not in itself a finding about the gene and the disease.
atherosclerosis (continued). "Fatty acid-binding protein 4 (FABP4), known as adipocyte FABP (A-FABP) or aP2, and FABP5, known as epidermal FABP (E-FABP) or mal1, are expressed in both adipocytes and macrophages and play an important role in the development of insulin resistance and atherosclerosis." (PMID 27936164, 2016). "FA binding protein 4 (FABP4) and FABP5, which are abundantly expressed in adipose tissues and macrophages, have been identified as key molecules in the pathogenesis of overnutrition-related diseases, such as insulin resistance and atherosclerosis." (PMID 24603714, 2014). "It has been shown that circulating FABP5 level is related to cholesterol efflux capacity as a quality marker of high-density lipoprotein (HDL) cholesterol and atherosclerosis in coronary and carotid arteries." (PMID 33071982, 2020). "FABP5 plays important roles in the development of several chronic diseases including cardiovascular disease where, as found for FABP4, macrophage-specific deletion of FABP5 was protective against development of atherosclerosis." (PMID 37207357, 2023). "In the cerebral artery, the interaction between MAPK1, FABP5 (recombinant human fatty acid-binding protein-5), and FN1 (fibronectin 1) was involved in the biological processes of response to wounding, which may accelerate the process of atherosclerosis." (PMID 34306013, 2021). "Interestingly, the concentration of FABP5, but not that of FABP4, has been reported to be negatively and independently associated with cholesterol efflux capacity from macrophages as a function of HDL cholesterol, suggesting a potential residual risk biomarker in atherosclerosis." (PMID 33071982, 2020).
cervical cancer (28 papers, 2018 to 2025). A primary or metastatic malignant neoplasm involving the cervix. "Shang and colleagues indicated that lymphangiogenesis is promoted by FABP5-mediated fatty acid metabolism in lymph node pre-metastatic niche through LNMICC (lncRNA associated with LNM in cervical cancer)." (PMID 34217300, 2021). "Furthermore, FABP5 is implicated in the promotion of epithelial-mesenchymal transformation, lymphangiogenesis, and cervical cancer lymph node metastasis through the reprogramming of fatty acid metabolism." (PMID 39928282, 2025). "FABP5 is highly expressed in cervical cancer, promoting lymph node metastasis and immunosuppression." (PMID 40717587, 2025). "Another study revealed the mechanism that FABP5 promoted fatty acid synthesis and lipolysis, which led to an increase in intracellular fatty acids thus inducing lymph node metastasis in cervical cancer." (PMID 38693136, 2024). "In cervical cancer, FABP5 reprograms lipid metabolism and facilitates epithelial-mesenchymal transition and lymph node metastasis via activating the NF-κB pathway." (PMID 37416772, 2023). "In an earlier cervical cancer study, FABP5 was shown to promote epithelial-mesenchymal transition and lymph node metastasis by reprogramming fatty acid (FA) metabolism." (PMID 37416772, 2023). "FABP5 has been found to promote lymph node metastasis in cervical cancer by reprogramming fatty acid metabolism." (PMID 36792587, 2023). "COL8A1 has been shown to promote non-small cell lung cancer progression by activating IFIT1/IFIT3-mediated EGFR signaling, while FABP5 can promote lymph node metastasis in cervical cancer by reprogramming fatty acid metabolism." (PMID 37795080, 2023). "lncRNAs have been reported to interfere with lymph node metastasis of cervical cancer, which promote FA metabolism reprogramming and cervical cancer cell metastasis via modulating FABP5—a carrier for FA uptake and transport." (PMID 35846429, 2022). "FABP5 can promote epithelial-mesenchymal transition, lymphangiogenesis, and lymph node metastasis in cervical cancer cells by regulating fatty acid metabolism." (PMID 36338999, 2022). "The mRNA and protein expression levels of FABP5 in cervical cancer (CCa) cells derived from lymph node metastatic sites (MS751) were significantly higher than those in CCa cells derived from primary sites (HeLa and SiHa)." (PMID 35445019, 2022). "Fatty acid-binding protein 5 (FABP5) may promote lymph node metastasis of cervical cancer by MR of fatty acid." (PMID 39588377, 2024). "Furthermore, the downregulation of FABP5 has the potential to inhibit cervical cancer cell proliferation, cell migration, colony formation and invasion capacity in vitro and to decrease tumor growth, to suppress metastasis activity in mouse." (PMID 38965292, 2024). "Similarly, the down-regulation of FABP5 in cervical cancer inhibits the in vivo and in vitro expression of MMP-2 and MMP-9." (PMID 35445019, 2022). "Additionally, it has been proved that high expression of FABP5 in positive connection with the presence of LNM of cervical cancers can induce expression of matrix metalloproteinase-2 and matrix metalloproteinase-9." (PMID 34217300, 2021). "Furthermore, it has been reported that CPTI expression is modulated by lncRNA-LNMICC that promotes metastasis of cervical cancer and this regulation depends on FABP5." (PMID 33050166, 2020). "FABP5 may serve as a biomarker for pelvic lymph node metastasis in cervical cancer." (PMID 40717587, 2025). "FABP5 activates NF-κB by promoting fatty acid metabolism, inducing epithelial-mesenchymal transition (EMT) and lymphangiogenesis, thereby facilitating cervical cancer metastasis." (PMID 40717587, 2025). "Resveratrol (RSV) directly interacts with FABP5, inhibiting fatty acid transport to the nucleus and downstream matrix metalloproteinases (MMP2 and MMP9), thereby suppressing cervical cancer metastasis." (PMID 40717587, 2025).
cervical cancer (continued). "Fatty acid-binding protein 5 (FABP5) is involved in fatty acid transport, and acts as a prognostic biomarker in cervical cancer, triple-negative breast cancer and clear cell renal cell carcinoma." (PMID 32775301, 2020). "Importantly, FABP5, as a promising predictor of LNM, promotes metastasis by reprogramming fatty acids metabolism in cervical cancers." (PMID 34217300, 2021). "In addition, lncRNA related to cervical cancer lymph node metastasis promotes fatty acid metabolism reprogramming by regulating fatty acid binding protein 5 (FABP5) and promoting cervical cancer lymph node metastasis." (PMID 33096860, 2020).
Insulin resistance (26 papers, 2011 to 2024). Increased resistance towards insulin, that is, diminished effectiveness of insulin in reducing blood glucose levels. "While both FABP4 and FABP5 were closely associated with insulin resistance and measures of adiposity, only FABP4 showed a decrease in concentration in response to the 6-month intervention with the FVJC supplement." (PMID 26688725, 2015). "The adipocytes of FABP5-deficient mice exhibited an enhanced capacity for the transport of insulin-dependent glucose and a modest increase in systemic insulin sensitivity while overexpressing FABP5 aggravated insulin resistance and hyperglycaemia." (PMID 35445019, 2022). "Loss or downregulation of Nr4a3 (Log2FC = −5.87), Scd1 (Log2FC = −2.24), Chrna4 (Log2FC = −4.23), and Fabp5 (Log2FC = −3.82) increase glucose intolerance, insulin resistance, diet-induced fatty liver disease, and cholinergic anti-inflammatory pathways." (PMID 35004828, 2021). "Previous studies using FABP4- and FABP5-deficient mice demonstrated that both FABP4 and FABP5 play significant roles in the development of insulin resistance, diabetes mellitus and atherosclerosis." (PMID 28303004, 2017). "FABP5 knockout mice showed an improvement in plasma triglycerides and cholesterol, as well as insulin resistance." (PMID 23476706, 2013). "FABP4/FABP5 genes (fatty acid binding proteins 4 and 5) are directly involved in the regulation of fat deposition, are mainly expressed in fat and bone marrow cells, and are related to the development of insulin resistance." (PMID 34419151, 2021).
colorectal cancer (18 papers, 2016 to 2026). A primary or metastatic malignant neoplasm that affects the colon or rectum. "In colorectal cancer, FABP5 promotes tumor progression by regulating lipid metabolism and cell proliferation-related signaling pathways." (PMID 40717587, 2025). "Here, we investigated the role of the fatty acid-binding protein 5 (FABP5) in colorectal cancer (CRC)." (PMID 37416772, 2023). "In colorectal cancer, FABP5 overexpression exerted an inhibitory influence on cancer progression by reducing lipid accumulation." (PMID 37858219, 2023). "We also showed that FABP5 regulated the expression of metabolic genes via an PPARβ/δ (peroxisome-proliferator-activated receptor β/δ)-independent pathway in colorectal cancer cells." (PMID 30167092, 2018). "Fatty acid-binding protein 5 (FABP5), a fatty acid-binding protein, was also identified as a crucial signature in the model and has been recognized as a novel target for its regulatory role in lipid metabolism in colorectal cancer." (PMID 38580967, 2024). "Although previous studies showed that FABP5-PPARβ/δ signaling induced the expression of genes involved in cell growth and survival, we recently demonstrated that FABP5 regulates the expression of metabolic genes via a PPARβ/δ-independent pathway in colorectal cancer cells." (PMID 30167092, 2018). "However, our recent study strongly suggested that FABP5 promoted cell growth and metastatic potency in colorectal cancer cells in a PPARβ/δ-independent manner." (PMID 30167092, 2018). "The present study demonstrates that the FABP5 gene is upregulated in colorectal cancer cells compared to normal colon cells in a manner that correlates with disease stage and that FABP5 significantly promotes colorectal cancer cell growth and metastatic potential." (PMID 27047747, 2016). "Thus, FABP5 might be a promising prognostic or therapeutic biomarker candidate in human colorectal cancer." (PMID 27047747, 2016). "Functional heterogeneity exists among subtypes: FABP7 drives glioblastoma stem cell migration via RXRα signaling, while FABP5 exhibits context-dependent roles, promoting HCC progression but suppressing colorectal cancer (CRC) through mTOR-mediated autophagy." (PMID 40717587, 2025). "We confidently identified known prognostic biomarkers for colorectal cancer, such as S100A4, LGALS1, and FABP5." (PMID 38580967, 2024). "Similarity, a similar study in colorectal cancer has also demonstrated the positive connection between ALKBH5 and FABP5." (PMID 37858219, 2023). "It was reported that the FABP5 and FABP6 were overexpressed and might play promoting roles in colorectal cancer." (PMID 27779102, 2016).
gastric cancer (16 papers, 2018 to 2025). A primary or metastatic malignant neoplasm involving the stomach. "Gastric cancer: FABP5 overexpression is closely associated with poor prognosis in gastric cancer." (PMID 40717587, 2025). "Overexpression of FABP5 significantly enhances the tumorigenic potential of gastric cancer cells in animal models, leading to increased intracellular fatty acid levels and promoting cancer progression." (PMID 40365984, 2025). "In esophageal cancer, gastric cancer, liver cancer, and colorectal cancer, studies have observed FABP5 overexpression, which correlates with tumor proliferation, invasiveness, and poor patient prognosis." (PMID 40178066, 2025). "Ectopic expression of FABP5 promotes gastric cancer proliferation, invasion, migration, and carcinogenicity." (PMID 40717587, 2025). "In summary, these findings suggest that the interaction between STAT5A and FABP5 is crucial for promoting fatty acid metabolism and tumor development in gastric cancer, highlighting it as a potential therapeutic target." (PMID 40365984, 2025). "STAT5A-dependent FABP5 expression plays a carcinogenic role in gastric cancer cells by reprogramming intracellular fatty acid metabolism." (PMID 39588377, 2024). "In all seven gastric cancer cell lines, either or both of FABP5 and NME1 knockdown would result in a significant reduction of proliferation, an increase of apoptosis." (PMID 37402315, 2023). "Studies have found that by influencing the FABP5 expression, which further affects the tumorigenesis of gastric cancer cells, STAT5A can contribute to the process of cellular lipid metabolism." (PMID 35517418, 2022). "In gastric cancer, FABP5 has been reported to enhance tumor growth, invasion, and migration." (PMID 39928282, 2025). "It was also presented that the silence of the FABP5 gene might attenuate the invasiveness of gastric cancer cells, detain cell proliferation, and arrest the cell cycle in the G0/G1 phase, leading to a significant increase in apoptosis." (PMID 32328135, 2020). "In conclusion, FABP5 and NME1 were not only identified as normal gastric corpus stem/progenitor markers, but also proven to be important for the propagation in gastric cancer cells." (PMID 37402315, 2023). "In addition, FABP5 gene silencing by RNA interference technology inhibited the proliferation and invasive properties of human SGC‐7901 gastric cancer cells in vitro and triggered a G0/G1 cell cycle arrest leading to apoptosis." (PMID 38965292, 2024). "In addition, the identified gastric stem/progenitor marker genes here, that is, FABP5 and NME1, are also important for the propagation in gastric cancers as proved by in vivo gastric cancer samples and several gastric cancer cell lines." (PMID 37402315, 2023). "Since FABP5 and NME1 were proven to be important for gastric epithelial stem/progenitor cells, we asked whether they also play a crucial role in gastric cancers." (PMID 37402315, 2023). "Importantly, FABP5 and NME1 were identified and validated as crucial for both normal gastric stem/progenitor cells and gastric cancer cells." (PMID 37402315, 2023). "Another protein, fatty acid-binding protein 5 (FABP5), has been reported to activate immune-related pathways, including cytokine–cytokine receptor interaction, interleukin-17 signaling, and tumor necrosis factor signaling, thereby stimulating LNM in gastric cancer." (PMID 39195316, 2024). "Thus, to test this hypothesis, we knocked down FABP5 and NME1 in seven different gastric cancer cell lines, including AGS, HGC-27, MGC-803, KATO III, NCI-N87, SNU-5, and SNU-16." (PMID 37402315, 2023).
glioma (16 papers, 2010 to 2025). A benign or malignant brain and spinal cord tumor that arises from glial cells (astrocytes, oligodendrocytes, ependymal cells). "Conversely, in high-risk pediatric gliomas, elevated FABP5 levels have been associated with a more favorable prognosis, highlighting clear differences in regulatory mechanisms between age groups." (PMID 40370434, 2025). "In adult tumors, such as glioma, cervical cancer, and liver cancer, FABP5 promotes malignant transformation via activation of the NF-κB pathway." (PMID 40370434, 2025). "By sponging mir-620, circABCB10 can up-regulate the expression of the FABP5 axis to promote tumoral growth and cancer cellularity in cerebral glioma and act as an oncogenic factor in glioma." (PMID 39727990, 2024). "FABP5 has also been proven to enhance the malignancy of lower-grade gliomas via canonical activation of NF-κB signaling." (PMID 36792587, 2023). "Other fatty acid-binding proteins such as FABP3, FABP5, FABP6 and FABP7 have been also implicated in glioma migration or invasion." (PMID 37120445, 2023). "Of these PA transporters, FAT/CD36 and FABP5 are highly correlated with decreased glioma patient survival, and both are expressed at significantly higher levels in IDHwt tumors." (PMID 36012521, 2022). "At the same time, circ-ABCB10 can sponge miR-620 and upregulate the expression of the FABP5 axis to promote tumor growth and proliferation in glioma." (PMID 35646916, 2022). "FABP5 was overexpressed in recurrent gliomas, consistently, was significantly enriched in recurrent LGGs." (PMID 33837625, 2021). "FABP4 and FABP5 are involved in tumorigenesis in different cancer types, including colorectal, prostate, oral, glioma, ovarian, and breast cancer." (PMID 33050166, 2020). "Thus, in many cell-based and in vivo studies, FABP5 deletion, knockdown, or inhibition has been shown to reduce cell proliferation, including in PC, glioma, colorectal cancer, gastric cancer, lung adenocarcinoma, and renal clear cell carcinoma." (PMID 37207357, 2023). "Furthermore, increased FABP5 was closely correlated with severe prognosis in either primary or recurrence gliomas, particularly among LGGs." (PMID 33837625, 2021). "Moreover, increased FABP5 expression could be observed along with the malignancy elevation of gliomas in CGGA dataset." (PMID 33837625, 2021). "Specific inhibitors targeting FABP5 and FAT/CD36 have been developed and successfully tested in other disease models, which can be applied to glioma research." (PMID 36012521, 2022). "Based on univariate and multivariate cox regression analysis, we identified five genes, FABP5, VEGFA, SAA1, ADM, and PRLHR, for prognosis prediction in patients with glioma." (PMID 35800054, 2022). "However, the functional role for FABP5 in glioma still remains unclear." (PMID 33837625, 2021). "Regarding FABP5, its overexpression is highly reported in cancers such as cervical, CRC, pancreatic, bladder cancer, or glioma, among others." (PMID 33050166, 2020). "In addition, circ-ABCB10 was reported to sponge miR-145-5p, affecting the miR-620/FABP5 axis, miR-1252 FOXR2, and miR-670-3p in oral squamous cell carcinoma, glioma, non–small cell lung cancer, and esophageal squamous cell carcinoma, respectively." (PMID 35646916, 2022). "Additionally, a predictive model based on five HUB genes (FABP5, VEGFA, SAA1, ADM, and PRLHR) was constructed to predict OS in patients with gliomas." (PMID 35800054, 2022). "The results indicated that FABP5 was predominantly enriched in the cytoplasm of glioma cells, while no significant staining was observed in the non‐tumour tissues." (PMID 33837625, 2021). "In addition, FABP5 was found to be expressed in 9 of 23 gliomas with moderate to strong cytoplasmic staining in Human Protein Atlas (HPA) database, and was reported to be expressed in grade II (19/30) and III (22/31) astrocytoma (a histologic subtype of glioma)." (PMID 32775301, 2020).
fatty liver disease (15 papers, 2011 to 2025). A reversible condition wherein large vacuoles of triglyceride fat accumulate in liver cells via the process of steatosis. "Hepatic lipid metabolism disorder:Exacerbates high-fat diet (HFD)-induced pathological hepatic steatosis (fatty liver).Elevates hepatic lipid metabolic parameters.Alters the expression of Fatty acid-binding protein 5 (FABP5)." (PMID 41158522, 2025). "Taken together, these results suggest that FABP5‐asprosin interaction promotes hepatic steatosis, inflammation, and fibrosis progression by inhibiting PPARα activity in mice." (PMID 40231957, 2025). "Furthermore, hepatocyte‐specific knockdown of FABP5 significantly reversed asprosin‐exacerbated hepatic steatosis in HFHFHC mice." (PMID 40231957, 2025). "Similarly, the exacerbation of hepatic steatosis, inflammation, and fibrosis induced by hepatocyte‐specific overexpression of asprosin in HFHFHC mice was also rescued by hepatocyte‐specific knockdown of FABP5." (PMID 40231957, 2025).